TOP2A (DNA topoisomerase II alpha)
Diseases named in the same sentence as TOP2A in open-access papers (continued):
Sharing a sentence is not in itself a finding about the gene and the disease.
cancer (continued). "Collectively, these findings indicate that TOP2A involved in tumor carcinogenesis and progression might be a prognosis biomarker in pan-cancer, especially in LIHC." (PMID 37980167, 2023). "TOP2A, CENPF, TROAP, CDC20, CDCA5, and UBE2C are all reported to be associated with cancer." (PMID 36932399, 2023). "In addition to TERT, BLCAP, and KBTBD8, we also observed low levels of damage induction in UV-irradiated melanocytes at a number of other recurrent mutations in the promoters of known or suspected cancer genes (i.e., TCF3, TOP2A, NUMB, FOSB, and OTUB2)." (PMID 37169747, 2023). "Taken together, TOP2A and Wnt3a may play an important role in VM formation and cancer progression in NSCLC." (PMID 37407689, 2023). "In addition, Zhang and colleagues have shown that TOP2A deletion can significantly inhibit the proliferation and migration of cancer cells and induce cell apoptosis." (PMID 38144520, 2023). "The correlation between TOP2A and cancer development has been explored in several cancers." (PMID 35012441, 2022). "In the case of TOP2A, targeting of the C-terminus would enable selective targeting of TOP2A while avoiding TOP2B, which is associated with some treatment-induced adverse events (i.e. toxic effects of cancer therapy)." (PMID 36699404, 2022). "Researchers have suggested that the HER2 status may influence the effect of TOP2A on inhibitors on cancer cells, and a significant correlation exists between the expression of RRM1 and ERCC1 and response to chemotherapy." (PMID 35711974, 2022). "Furthermore, TOP2A was positively associated with expression of immune checkpoints (CD274, CTLA4, HAVCR2, LAG3, PDCD1 and TIGIT) in most cancer types." (PMID 35778520, 2022). "Besides, we performed TOP2A expression in other cancer types which include the normal tissues from GTEx project as controls." (PMID 35778520, 2022). "Accordingly, TOP2A is involved in chromosome formation, enrichment, and separation, in DNA replication and transcription, and it is suggested to be involved in the development of several cancer types." (PMID 35884419, 2022). "TOP2A also conferred platinum resistance in several human cancers." (PMID 35078445, 2022). "The configuration of 17q21 amplifiers in cancer cells may influence the effect of HER2 on TOP2A inhibitors, thereby affecting the efficacy of these chemotherapeutic drugs." (PMID 35711974, 2022). "However, some studies verified that the higher expression of TOP2A has nothing to do with the worse prognosis in these cancer types." (PMID 35778520, 2022). "In addition, high expression of TOP2A was related to the cell cycle, and targeting TOP2A is also considered to be an important method for treating human cancer." (PMID 36247089, 2022). "Besides, the high frequency of TOP2A genetic alterations was observed in several cancer types, and related to prognosis in some cases." (PMID 35778520, 2022). "Increasing studies have revealed significant associations between TOP2A with oncogenesis and prognosis of human cancers; however, pan-cancer analysis has not been reported." (PMID 35873470, 2022). "In addition, we employed the “Pathological Stage Plot” module of GEPIA2 to observe the correlation between TOP2A expression and the pathological stages of cancers." (PMID 35778520, 2022). "Among the top genes we selected that were consistently overexpressed after brain ischemic injury, Top2a has been reported to accelerate tumor development and progression in many cancers, whose upregulation correlated with tumor metastasis and shorter survival in patients." (PMID 36605216, 2022). "It is noteworthy that different topoisomerase family genes may have an up- or down-regulation in the same types of cancer, such as TOP2A and TOP3B in KIRC." (PMID 36288358, 2022).
cancer (continued). "Given the importance of tumor-immune cell infiltrations in the initiation, development, and metastasis of cancers, the potential relationships between the TOP2A expression level with the tumor-immune cell infiltrations were analyzed in different estimations algorithms based on the TCGA database." (PMID 35873470, 2022). "In addition, TOP2A expressions in different cancers are suggested as the favorable prognostic biomarker that predict cancer progression and relapse, and it also serves as the risk factor for dismal survival." (PMID 34939898, 2021). "As will be discussed later, this latter point is critical because HER2- amplified cancers that have co-amplification of the topoisomerase 2 gene locus—TOP2A, may be uniquely sensitive to anthracyclines." (PMID 34625570, 2021). "TOP2A functions as an oncogene in various cancers, including OC." (PMID 34787052, 2021). "A significantly high expression level of TOP2A has been reported in many types of cancers." (PMID 34384030, 2021). "Furthermore, reverse relationships between miRNA‐145‐5p and TOP2A were observed in 14 different cancers." (PMID 33527765, 2021). "TOP2A has been reported to be a significant cancer progression-related gene." (PMID 34787052, 2021). "TOP2A regulates various signaling pathways and participates in the evolvement of cancer." (PMID 34787052, 2021). "Furthermore, HCC tissues were collected to demonstrate that the expression levels of TOP2A were higher within HCC samples as compared with healthy non-carcinoma samples." (PMID 34939898, 2021). "Excessive TOP2A leads to uncontrolled proliferation; as such, combined HDACi and topoisomerase inhibitors are hypothesized to induce apoptosis in cancer." (PMID 32673289, 2020). "Ubiquitinations were identified throughout the Top2α sequence in cancer cells." (PMID 35582608, 2020). "In this region, three phosphorylations could be identified in cancer cells and only one thus far in normal cells, including phosphorylation on Ser1525, which could modulate binding of Top2α to the nucleosome." (PMID 35582608, 2020). "By analyzing “Bittner Multi-cancer”, a multi-cancer microarray dataset using Oncomine, we observed that TOP2A and CENPF expression was higher (Student’s t-test, P = 2E-7 and 3E-4 respectively) in CC than other 15 cancer types, confirming the RNA-seq data from TCGA and the GTEx." (PMID 33023625, 2020). "TOP2A is a gene that involves copy number variations and chromosomal instability in many cancers." (PMID 32153633, 2020). "CCNB1, CKS2, MKI67, RRM2, TK1 and TOP2A were found with positive clinical correlation to GLEASON SCORE, and we could clearly identify the core factors as cancer risk factors, the expression level increased as Gleason score elevated." (PMID 32266115, 2020). "TOP2A has been studied the most among the hub genes and it affects multiple cancer types." (PMID 33126319, 2020). "Although no drug resistant mutations targeting known PTM sites could be found in the literature except for vosaroxin resistant yeast cells, it cannot be excluded that such events occur in the Top2α gene of resistant cancer cells." (PMID 35582608, 2020). "Nonetheless, even among the unselected genes, there were some well-known cancer-related genes, including TOP2A, as its interacting proteins, and its modified abnormal alterations may play an important role in CIN in human cancers." (PMID 32196072, 2020). "Several lines of evidence show that TOP2A regulate signaling pathway in cancer." (PMID 32201520, 2020). "TOP2A was closely related to the proliferation of various cancer cells." (PMID 33240085, 2020). "Although less abundant, six phosphotyrosines in the Top2α protein were identified in cancer cells." (PMID 35582608, 2020). "Besides the relatively high expression in cancers comparing to normal tissues, TOP2A expression was tend to be higher in male and smoker patients comparing to female and non-smokers." (PMID 31528121, 2019).
cancer (continued). "Etoposide, another inhibitor of TOP2A, might inhibit the progress of cancer by inducing DNA damaging." (PMID 31139019, 2019). "All the bioinformatic analysis and qRT-PCR experimental results support the hypothesis that TOP2A potentially regulate NSCLC cancer development through co-work with TPX2." (PMID 31528121, 2019). "Exposure to anti-cancer drugs, especially those targeting DNA topoisomerases may change the expression pattern of Top2α and Top2β genes." (PMID 31791417, 2019). "Furthermore, we show that HMGA2 significantly reduced genotoxic DNA damage in each tested cancer cell model during treatment with the TOP2A poison etoposide or the catalytic TOP2A inhibitor merbarone." (PMID 31271486, 2019). "Moreover, TOP2A is the target for some of the most widely used chemotherapeutic drugs for treatment of human cancers." (PMID 31216997, 2019). "Thereby, TOP2A remains as the vital therapeutic target of anti-cancer drugs." (PMID 31412643, 2019). "TOP2A is the target of etoposide, which has been used in cancer treatment." (PMID 30123134, 2018). "Interestingly, pixantrone, a compound structurally-close to anthracyclines, has been shown to target more effectively Top2α than Top2β in living cancer cells." (PMID 30404148, 2018). "Highly increased expression level of TOP2A in NSCLC tissues is closely related to the malignant biological behaviors of this cancer such as proliferation and invasion, and interference with TOP2A expression inhibits the proliferation and invasion of NSCLC cells." (PMID 30369945, 2018). "To validate RT-LAMP based on the expression of TOP2A in different cell types (whether cancer epithelium or stroma), we performed label-free FTIR imaging on the same section prior to amplification." (PMID 29335461, 2018). "Interestingly, a synthetic phenanthridine alkaloid (NK314) has been shown to act as a Top2α-specific poison in cancer cells." (PMID 30404148, 2018). "TOP2A was a gene that involves copy number variation and chromosomal instability in many cancers." (PMID 29651323, 2018). "In this setting, only cancer epithelium are expected to express TOP2A." (PMID 29335461, 2018). "TOP2A plays a vital role in both cancer-inhibiting and cancer-promoting processes." (PMID 30544723, 2018). "The alteration of TOP2A in gene copy number and gene expression level is usually found in cancer cells, and deregulation of TOP2A expression might play an important role in chromosome instability and tumorigenesis." (PMID 30065754, 2018). "TOP2A has been found to be aberrantly expressed in a variety of solid tumors, and it plays an important role in occurrence and development of malignant tumors." (PMID 28355294, 2017). "Here, we showed that fisetin inhibited the transcription of topoisomerase II A (TOP2A) enzyme in human HepG-2 and Suit-2 cancer cells and that could be responsible, in part, for the anti-tumor effect of fisetin on those cells." (PMID 28052097, 2017). "The TOP2A gene is overexpressed in several cancer types and is hypothesized to predict sensitivity to anthracycline-based therapies." (PMID 27888622, 2017). "As drugs such as doxorubicin, etoposide, and mitoxantrone have been designed to target TOP2A in cancer patients, other hubs of this group may also have the potential as functional therapeutic targets to modify targeted therapy outcomes." (PMID 28892521, 2017). "HER2 and TOP2A genes are coamplified in breast and some other cancers." (PMID 25695068, 2015).
cancer (continued). "Despite a reported correlation between high levels of TOP2A and poor outcome in cancer, the exact mechanism underlying more aggressive phenotype associated with TOP2A is not known." (PMID 26560244, 2015). "While the biochemical and biophysical data confirmed that the compounds from the HTS can target Top2α and affect their enzymatic properties, it is important to demonstrate that they are cytotoxic toward cancer cells and thus have the potential to be developed as anti-cancer drugs." (PMID 24809695, 2014). "The depletion of TOP2B and TOP2A in tumors may suggest an explanation for the reported DRZ interference with cancer response to anthracyclines." (PMID 25406834, 2014). "Cytotoxicity was most potent in A498 cells which may resulted from TOP2α and β expression levels were higher than other cancer cell lines." (PMID 25372714, 2014). "Overexpression and/or amplification of TOP2A have been observed in many types of cancers." (PMID 23928695, 2013). "However, as it was found that TOP1/TOP2A expression in cancer cells are important in determining the cellular response to chemotherapeutics." (PMID 24103454, 2013). "Previous studies have shown that the chemosensitivity of TOP2A poisons could be regulated by the expression level of TOP2 protein in cancer cells." (PMID 24103454, 2013). "Beyond its physiological functions, TOP2A is reported to be a sensitive and specific marker of actively proliferating cells (in the late S, G2 and M-phases of the cell cycle), which suggests the importance of its investigation in cancer." (PMID 23398928, 2013). "The selective degradation of TOP2B could prevent ANT-induced damage to the cardiomyocyte genome due to poisoning by this isoform and subsequent DNA double-strand breaks while sparing the TOP2A isoform in cancer cells." (PMID 24116135, 2013). "The implications for TOP2A amplification in cancer are better known." (PMID 22292074, 2012). "Thus, up-regulated levels of TOP2A protein are found in proliferating cancer cells, and TOP2A is essential for the viability of these dividing cells." (PMID 22111588, 2011). "Several genes encoding protein products that are important in cancer and have functions related to cell cycle, growth, DNA replication and protein translation (such as CCND1, TOP2A, TOPBP1, TFRC; three members of H4 histone family [HIST1H4C, HIST1H4B, and HIST1H4E]; and EIF4G1)." (PMID 17498291, 2007). "Therefore, exploring natural TOP2A inhibitors from Chinese herbal medicine could provide valuable opportunities for cancer chemoprevention and therapy." (PMID 41301416, 2025). "A significant factor in chromosomal instability and carcinogenesis is abnormal TOP2A expression, strongly correlated with the initiation, incursion, course of treatment, and prognosis of malignant tumours; demonstrated to be an effective therapy against cancer." (PMID 39911278, 2025). "Furthermore, upregulation of TOP2A is associated with a negative prognosis, increased tumor grades, and stages, suggesting its involvement in cancer aggressiveness." (PMID 38895552, 2024). "TOP2A is part of the topoisomerase protein family that facilitate replication and the ability of malignant tumors cells to undergo infinite proliferation, and topoisomerase inhibitors are used in the clinic for treating several other types of cancer by inhibiting this mechanism." (PMID 36656469, 2023). "According to the proteomics, although the expression of TOP2A was also reduced for this comparison, there were multiple other changes in the DNA damage recognition/repair machinery that affected the overall outcome (e.g., reduction in breast cancer gene 2, BRCA2 and gain in PARP1)." (PMID 37242727, 2023). "Additionally, TOP2A expression levels are associated with a poor prognosis; previous studies reported that TOP2A could serve as a potential prognostic indicator and target for cancer therapy." (PMID 35251970, 2022).
cancer (continued). "However, it remains unclear whether TOP2A plays a role in pathogenesis of different cancers through some common molecular mechanisms." (PMID 35778520, 2022). "However, current research on TOP2A focus on single or limited cancer types." (PMID 35873470, 2022). "Therefore, it is time to explore the pan-cancer evidence of the biological functions of TOP2A cross-carcinoma to reveal the pathogenesis of TOP2A in different cancers or the potential molecular mechanisms in the clinical prognosis, so as to develop more specific treatments for various cancer types." (PMID 35873470, 2022). "Etoposide, an inhibitor of TOP2A, could inhibit the development of cancer by inducing DNA damage." (PMID 34596112, 2021). "In summary, the novel skeleton compound cyclizing-berberine A35, which has an inhibitory mechanism on the top2α catalytic cycle different from that of other topoisomerase inhibitors, could strongly inhibit cancer proliferation and induce G2/M arrest, especially M-phase arrest." (PMID 29728107, 2018). "Thus, therapy-related chromosomal translocations causing secondary cancers can be due to poison interference with Top2β rather than Top2α." (PMID 30404148, 2018). "Thus, Top2α is considered a marker of cell proliferation, and expression studies in normal human tissues and cancers have shown that it is often overexpressed in aggressive or rapidly proliferating tumors, while it is undetectable in differentiated and quiescent cells." (PMID 30404148, 2018). "Interestingly, TOP2A presented the same trend of gene expression change between the sensitive groups and resistant groups of the tumor patients as observed in the docetaxel sensitive and resistant cancer cells." (PMID 26824188, 2016). "Given the biological importance of TOP2α, its inhibition in cancer therapy, and the role ubiquitylation plays in regulating its turnover and activity, it is of importance to identify other E3 ligases that may ubiquitylate TOP2α." (PMID 27558965, 2016). "In addition, our data suggest that these functional interactions between RNF168 and TOP2α may play important roles in the response and resistance of tumors to anti-cancer drugs that target TOP2." (PMID 27558965, 2016). "Our screening platform may produce new types of potential anti-cancer agents targeting Top2α." (PMID 24809695, 2014). "Therefore, the exploration of differences in structure and function between the two Top2 isoforms is important, and the development of selective Top2α inhibitors may be a beneficial strategy in the search for new cancer drugs with improved clinical safety." (PMID 25489853, 2014). "Using teniposide (VM26) as a model compound for our screening assay, we tested whether a number of commonly employed denaturing reagents including alkali and SDS can allow for detecting the enhanced stability of the Top2α-DNA complexes in the presence of an anti-cancer drug." (PMID 24809695, 2014). "Proteins, including TOP2A, BPI, PSAT1, ANLN, and TFRC, were upregulated in five of the six cancer types." (PMID 41049442, 2025). "For the polar aqueous fraction, the hub proteins obtained by evaluating the overexpressed genes in the three types of cancer (BRCA, COAD, and LUAD) were TYMS, CDKN1, TOP2A, AURKA, and TK-1." (PMID 40430485, 2025). "Since migration and invasion are key hallmarks of cancer that drive tumor progression and metastasis, we investigated how NEIL3 and TOP2A influence these processes in EC cells." (PMID 39910812, 2025). "In contrast to TOP2A, the remaining three genes—ABLIM1, FHL5, and MAP3K8—exhibit more context-dependent roles in cancers." (PMID 40831931, 2025). "TOP2A and MCM2 were present in higher amounts per cell in PCS lysates compared to cancer cell lines." (PMID 40507244, 2025).